INS (insulin)
Diseases named in the same sentence as INS in open-access papers (continued):
Sharing a sentence is not in itself a finding about the gene and the disease.
Insulin resistance (continued). "The promotion of mitochondrial oxidative stress associated with the deletion/inhibition of NOX4 in hepatocytes diminished insulin signaling, whereas NOX4 deficiency in vivo promoted hepatic and systemic insulin resistance, a key driver of NAFLD." (PMID 38060313, 2023). "VLCKD effectively decreased fasting blood glucose, insulin, insulin resistance (measured by HOMAIR), triglycerides, total cholesterol, LDL cholesterol, HDL cholesterol, and GT in terms of metabolic parameters." (PMID 37892542, 2023). "Butyrate improved fasting glucose, insulin levels, homeostasis model assessment for insulin resistance (HOMA-IR) and insulin tolerance." (PMID 36909336, 2023). "Adiponectin is involved in the lowering of blood glucose and lipids, preserving insulin to remain sensitive, as well as expressed highly in the oxidation of fatty acid, while leptin takes part in abnormal conditions such as obesity and insulin resistance." (PMID 37175792, 2023). "Upon an insulin resistance state, insulin secretion from the pancreas is increased in an attempt to achieve normoglycemia." (PMID 36901787, 2023). "Insulin sensitizing effects: Melatonin's capacity to enhance insulin sensitivity is crucial in managing PCOS, where insulin resistance is a hallmark feature." (PMID 38106751, 2023). "Further, in nonalcoholic fatty liver disease mouse models thromboxane A2 (precursor to thromboxane B2) has been shown to contribute to insulin resistance by impairing insulin signaling." (PMID 37726331, 2023). "The main molecular feature of metabolic syndrome is insulin resistance, characterized by a reduced sensitivity to insulin and increased insulin secretion." (PMID 37370771, 2023). "Acute insulin resistance manifests as insulin-mediated glucose uptake reduction, mainly due to defective post-receptor insulin signaling and down-regulation of GLUT-4." (PMID 37025208, 2023). "Insulin resistance refers to the decreased response of the liver, muscles, and adipose tissue to insulin, leading to symptoms such as hyperglycemia, dyslipidemia, visceral obesity, and elevated inflammatory factors." (PMID 37569372, 2023). "Meanwhile, long-term trials reported meaningful improvements in T2DM indicators such as haemoglobin A1C (HbA1c), fasting glucose, fasting insulin, C-peptide, and markers of insulin resistance like homeostatic model assessment (HOMA)." (PMID 37836506, 2023). "The HE-treated sheep had a greater insulin:glucose ratio (p = 0.033), a greater estimated homeostatic model assessment of insulin resistance (HOMAIR; p = 0.029), and a reduced revised quantitative insulin sensitivity check index (RQUICKI; p = 0.015)." (PMID 37238121, 2023). "This ultimately results in hyperglycemia; and an increase in insulin secretion in the early stages of T2D as part of the compensatory mechanism that aims to counteract the presence of insulin resistance in T2D." (PMID 36672202, 2023). "For example, anthocyanins have been found to improve insulin resistance, normalize insulin signaling, reduce body weight, and correct abnormal liver function by reducing circulating ceramides." (PMID 38274826, 2023). "Preliminary data suggested significant improvements in body weight and composition, metabolic profile (glucose, serum insulin, triglycerides, total and low-density lipoprotein cholesterol), and insulin resistance following VLCKD." (PMID 36695999, 2023). "We therefore clarify how testosterone induces insulin resistance in female adipocytes and impairs insulin-mediated glucose uptake through the activation of selective metabolic signaling pathways and androgen receptor alterations." (PMID 37374053, 2023). "Some authors propose that insulin resistance participates in the promotion of autoimmune diabetes due to the increase in insulin demand, and this can accelerate the appearance of the disease in people with an autoimmune process." (PMID 37120620, 2023).
Insulin resistance (continued). "It is possible that α-cells develop insulin resistance, including blunted insulin-stimulated Akt phosphorylation, during chronic exposure to high glucose and insulin." (PMID 37159865, 2023). "Exosomes released from adipose-derived macrophages lead to glucose intolerance and insulin resistance, and these exosomes target PPARγ, which is highly expressed in adipocytes, to reduce insulin sensitivity of other tissues (e.g., the liver)." (PMID 36818396, 2023). "Cluster 1 (n = 103 (11.6%)) was characterized by high BMI, insulin resistance, high insulin secretion, an abnormal lipid profile, and higher kidney damage and was labeled as “obese insulin resistant with sufficient compensatory insulin secretion” (IR-SIS)." (PMID 36769457, 2023). "Accordingly, human clinical trials are needed to confirm its effectiveness on hemoglobin A1c (HbA1c), fasting blood sugar (FBS), blood insulin level, and insulin resistance as a complementary for better control of type 2 diabetes." (PMID 38028721, 2023). "When insulin resistance increases, the glycemic control function of insulin decreases, and the intracellular insulin signaling process deteriorates." (PMID 36834911, 2023). "These animal studies suggested that Metrnl has strong insulin sensitization and antagonizes insulin resistance in vitro; its specific dosage, duration, effects, and mechanism need further study." (PMID 36911663, 2023). "Based on the clinical data analysis results, the levels of insulin resistance‐related factors were assessed in SK‐Hep‐1 cells treated with MSG to evaluate the association between glutamate and insulin." (PMID 37314019, 2023). "Insulin resistance is characterized by a diminished response to insulin stimulation that results, in part, from disruption of the insulin signaling pathway." (PMID 37032433, 2023). "Insulin resistance occurs when pancreatic beta islets fail to produce and/or secrete sufficient insulin to fulfil metabolic needs, or when insulin-sensitive organs lose their capacity to respond to insulin stimulation." (PMID 37375802, 2023). "The two classes of oral insulin-sensitizing drugs that have been used to counter insulin resistance are thiazolidinediones (TZDs) which include troglitazone, Rosiglitazone, and pioglitazone) and the biguanide metformin." (PMID 37362539, 2023). "Homeostasis model assessment estimated insulin resistance (HOMA-IR) was calculated using the following formula: HOMA-IR = fasting insulin (FINS) (mU/L) × FBG (mmol/L)/22.5." (PMID 37034166, 2023). "Previous studies have confirmed that diabetes-related indicators (fasting insulin, FINS, fasting plasma glucose, FPG, glycated hemoglobin, HbA1c, insulin resistance, IR) were related to the risk of bone mineral density (BMD) and OP9–12." (PMID 37258550, 2023). "Insulin resistance is defined as an inadequate response of target tissues to insulin stimulation, primarily the liver, adipose tissue, and muscles." (PMID 37998747, 2023). "The pathogenesis of PTDM is very complex and includes both impaired insulin secretion and tissue insulin resistance." (PMID 37628646, 2023). "It is suggested that epimedin C improves the secretion function of pancreatic β-cells, attenuates insulin resistance, increases serum insulin contents, promotes hepatic glycogen synthesis, and keeps FBG nearly constant in T2DM mice." (PMID 38201855, 2023). "The effect of aerobic training on insulin resistance has been extensively studied, and it has been found to improve muscle insulin sensitivity by increasing the number of insulin receptors." (PMID 37512005, 2023). "On the contrary, it has been shown that serum testosterone levels at the normal range are needed to maintain appropriate insulin sensitivity in male rats and that both castration and high serum testosterone levels are followed by marked insulin resistance." (PMID 38068890, 2023).
Insulin resistance (continued). "Lipid overload induces insulin resistance in skeletal muscle and liver, thereby leading to defects in insulin-mediated glucose uptake and suppression of HGP, respectively." (PMID 37960324, 2023). "In contrast, the gene expression profiles identified here, which represent a muscle-specific state of individual insulin resistance, have predictive potential for the characterisation of individual insulin sensitivity." (PMID 36790478, 2023). "Myocyte lipids play an important role in inducing insulin resistance, and many lipid intermediates affect insulin signaling, resulting in lipotoxicity." (PMID 36918975, 2023). "With regard to the cause of GDM, three different phenotypes are currently considered: prevailing insulin resistance, impaired insulin secretion or their combination." (PMID 36676086, 2023). "Deficit in insulin secretion and high insulin resistance increase the lipase enzyme activity gradually leading to impairment of free fatty acid (FFA) metabolism and exceeding the amount of FFA beyond the liver’s ability to oxidize." (PMID 37674617, 2023). "Together, these three enriched pathways highlight an overall perturbation of insulin-related processes and insulin resistance in AA-SScL fibroblasts." (PMID 36835058, 2023). "In the 9th and 12th weeks, mice in the HF group presented with notably higher serum insulin and insulin resistance indexes than mice in the NF group (P < 0.05)." (PMID 37830511, 2023). "This is a case of a 26-year-old male patient, with relapsing Hodgkin lymphoma, treated with nivolumab and brentuximab-vedotin, who was admitted with hyperglycemia and severe insulin resistance requiring approximately 2000 units of intravenous insulin per day." (PMID 37942131, 2023). "It is caused by a failure to either produce sufficient insulin, or to consume insulin efficiently (insulin resistance)." (PMID 37111148, 2023). "It is reasonable that BCAAs give rise to an altered insulin-regulated metabolism in the early stages, while insulin, in turn, incurs the accumulation of BCAAs in the later stages of insulin resistance." (PMID 37755297, 2023). "In Type 2 diabetes, insulin resistance elicits compensatory insulin hypersecretion, provoking β-cell stress and eventually compensatory failure." (PMID 37626210, 2023). "In the setting of insulin resistance, the vasodilatory effect of insulin is lost but the effect on renal sodium reabsorption is preserved; thereby causing an increase in blood pressure." (PMID 36964104, 2023). "Particularly high levels of circulating amino acids and increased fat have been shown to contribute to nutritional overload, which boosts mTOR activation and can trigger insulin resistance in peripheral insulin-responsive tissues." (PMID 37762060, 2023). "A large proportion of these studies (21/38) reported on blood levels of glucose or insulin; some also measured glucose intolerance or insulin resistance." (PMID 36827239, 2023). "Several studies have showed a decrease in oxidative stress in diabetes after a MT treatment in parallel with an increase in insulin sensitivity and/or a decrease in insulin resistance." (PMID 37107334, 2023). "T2D is characterized by insulin resistance and β-cell failure and has been treated with thiazolidinediones (TZDs) for many years due to their ability to induce insulin sensitivity and reduce glycemia." (PMID 37189379, 2023). "Prolonged inflammation and OS overload can lead to impaired insulin secretion, insulin resistance, and further T2DM development." (PMID 37759802, 2023). "Insulin resistance (IR) is an inappropriate cellular response to insulin hormone in insulin-dependent cells." (PMID 36671511, 2023). "For instance, growth hormone induces insulin resistance but promotes insulin production whereas IGF-1 promotes insulin sensitivity and reduces insulin secretion." (PMID 37854186, 2023).
Insulin resistance (continued). "Insulin resistance (IR) is defined as a physiological status in which insulin-targeting tissues display reduced responsiveness to elevated physiological insulin levels." (PMID 38041100, 2023). "Dysregulated lipid homeostasis impairs the metabolic activities of insulin, leading to insulin resistance in TD2M patients." (PMID 37715850, 2023). "A central characteristic of insulin resistance is the impaired ability for insulin to stimulate glucose uptake into skeletal muscle." (PMID 36807886, 2023). "Studies have shown that taking additional folate can help people with type 2 diabetes better control their blood sugar levels by lowering glycosylated hemoglobin, fasting glucose, insulin levels, insulin resistance, and homocysteinemia." (PMID 37123774, 2023). "The Homeostatic Model Assessment for Insulin Resistance (HOMA-IR) was used as a measure of insulin sensitivity." (PMID 37891561, 2023). "Two variants associated with the 15th percentile of z-insulin were located on genes previously linked with insulin secretion and beta cell function (RBFOX1) and measures of insulin resistance (SH3RF3)." (PMID 37420130, 2023). "Patients with NIDDM usually have insufficient insulin secretion and insulin resistance concurrently." (PMID 36983587, 2023). "The HOMA-IR value for the NPD was within the insulin sensitivity range (<1.0), whereas it was significantly higher for the PD group and within the insulin resistance range." (PMID 38024366, 2023). "Dysregulation of lipid metabolism in the liver also negatively influences insulin sensitivity in energy metabolism–competent organs such as skeletal muscle and adipose tissue, which is followed by the progression of insulin resistance, or vice versa." (PMID 36834633, 2023). "In the prediabetes stage, as insulin resistance sets in and the first phase of insulin response starts to diminish, resulting in β-cells overworking to compensate for the reduced insulin levels." (PMID 37109458, 2023). "Insulin resistance occurs when vital tissues that respond to insulin, such as muscle, liver, and adipose tissue, become less receptive." (PMID 38283440, 2023). "Specifically, we compared obese individuals with insulin resistance to a group of individuals who exhibited insulin sensitivity." (PMID 37836502, 2023). "Insulin resistance means that systemic target tissues such as fat, muscle, and liver are less sensitive to insulin and cannot properly regulate the pathological state of glucose homeostasis." (PMID 37077347, 2023). "Due to insulin resistance, pancreas β cells need to secrete more insulin to control blood sugar, and the body then appears hyperinsulinemic, revealed by a research consistent with the results of this study." (PMID 37830511, 2023). "The best clinical surrogate marker of adipose insulin resistance is the product of fasting serum insulin times fasting free fatty acids, FFA." (PMID 38260129, 2023). "Modulation of SIRT1/AMPK and Akt/mTOR pathways is crucial in reducing insulin levels, insulin resistance, glucotoxicity and lipotoxicity, and in increasing ketogenesis." (PMID 37152929, 2023). "In patients with DM, hyperglycemia occurs due to insulin dysfunction or insulin resistance, preventing glucose from entering the cells." (PMID 37370930, 2023). "Insulin resistance is characterized by attenuated insulin-dependent glucose uptake in relevant target tissues, such as muscle and fat, and it plays a central role in cardiometabolic diseases." (PMID 38149844, 2023). "Insulin resistance is the inability of a known dose of exogenous or endogenous insulin to stimulate glucose uptake and metabolism in an individual to the same extent that it does in the general population in good health." (PMID 38203349, 2023). "Increased TNF‐α levels impair insulin signalling through serine phosphorylation, which induces insulin resistance and leads to the development of T2DM." (PMID 37257051, 2023).
Insulin resistance (continued). "This is presumed to be the result of reduced FBG despite lowered insulin levels due to reduced insulin resistance by CLM." (PMID 36934269, 2023). "Insulin resistance refers to impaired sensitivity to insulin mediated glucose disposal, resulting in a compensatory increase in beta-cell insulin production." (PMID 37762302, 2023). "Because insulin resistance is directly involved in excess hepatic fat accumulation, many types of insulin sensitizers were tested and histological benefits of thiazolidinediones were demonstrated in patients with NASH." (PMID 37111106, 2023). "A study performed among obese subjects with OHS revealed that continuous positive airway pressure (CPAP) therapy improved metabolic parameters, insulin sensitivity, and the Homeostatic Model Assessment for Insulin Resistance (HOMA-IR) scores." (PMID 37298632, 2023). "A recent metanalysis concerning the effect of PEG on glucose metabolism has shown a significant decrease in fasting glucose (FG), fasting insulin (FI), glycosylated haemoglobin (HbA1c), and the index of insulin resistance HOMA-IR during PEG monotherapy." (PMID 36892739, 2023). "Individuals with high insulin sensitivity had sustained ACTH suppression at lower glucose concentrations compared to individuals with insulin resistance." (PMID 36752854, 2023). "Although HOMA‐IR is commonly used as a parameter of insulin resistance in terms of convenience, the hyperinsulinemic‐euglycemic clamp can evaluate insulin sensitivity in not only the whole body but also in organs such as the liver, fat, and muscle." (PMID 36585794, 2023). "Overweight and obesity are related to insulin resistance (IR), defined as a defect in the insulin-mediated control of glucose metabolism, predominantly in muscle, fat and liver tissues." (PMID 37513538, 2023). "Although rats differ from humans, Wistar rats can develop insulin resistance following exposures that impact insulin sensitivity in humans." (PMID 37049441, 2023). "CNB-001 restored PA-induced insulin resistance and impaired insulin signaling by improving insulin-stimulated glucose uptake and increasing insulin-stimulated p-IR, p-IRS-1, and p-AKT expression levels." (PMID 37762669, 2023). "It is a metabolic disorder characterized by a dysregulated glucose metabolism resulting from impaired insulin secretion or insulin resistance." (PMID 36829576, 2023). "Previous studies have shown that hypertriglyceridemia affects glucose regulation and insulin sensitivity, and both high glucose levels and insulin resistance play an essential role in the pathogenesis of DCM." (PMID 36908240, 2023). "In comparison, type 2 DM (DM-II), which includes more than 90% of DM cases, is initially characterized by different degrees of insulin resistance (IR), followed by a progressive decrease in insulin secretion." (PMID 37187644, 2023). "Both animal and human experiments have demonstrated that the direct injection of LPS can increase fasting blood glucose and insulin levels, resulting in hyperinsulinemia and insulin resistance." (PMID 36902554, 2023). "In contrast, Oscillospira showed a negative correlation with body weight, fat accumulation (RFT and IFT, insulin resistance (Glucose, insulin, and HOMA-IR), and lipid profiles (LDL and HDL cholesterol)." (PMID 37705572, 2023). "Treatment with CA improved insulin resistance as evidenced by a reduction of insulin level in PCOS rats." (PMID 37483646, 2023). "Last, we detected a significant improvement in insulin sensitivity of young male Irs1KO mice, whereas a previous hyperinsulinemic-euglycemic clamp study found evidence of insulin resistance in the muscle of Irs1KO mice." (PMID 36812323, 2023). "The study indicated significant differences in fatty acids between individuals with insulin sensitivity and insulin resistance who engaged in physical activity, including monohydroxy, dicarboxylate, medium and long chain, mono and polyunsaturated fatty acids." (PMID 37175541, 2023).